CD81 (CD81 molecule)
Diseases named in the same sentence as CD81 in open-access papers (continued):
Sharing a sentence is not in itself a finding about the gene and the disease.
periodontitis (7 papers, 2020 to 2025). An acute or chronic inflammatory process that affects the tissues that surround and support the teeth. "The first study highlights the association between reduced levels of CD9 and CD81 exosome-related tetraspanins in saliva and periodontitis, particularly in more severe cases." (PMID 38192959, 2023). "However, only CD81 remained independently associated with periodontitis after adjusting for confounding variables, whereas the association of CD9 was attenuated by demographic covariables, limiting its diagnostic relevance." (PMID 41322905, 2025). "Further analysis of the C3 pathway showed that the C3 receptor–ligand pair was active in the communication between CD81+ fibroblasts and neutrophils in both healthy and periodontitis conditions, underscoring its unique role in neutrophil recruitment." (PMID 40801798, 2025). "Metformin alleviates inflammation and bone resorption in the ligature-induced periodontitis (LIP) model via inhibiting the interaction between CD81+ fibroblasts and neutrophils." (PMID 40801798, 2025). "Patients with stages II, III, and IV exhibited lower CD9 concentrations than those with stage I periodontitis, while CD81 levels were significantly reduced in stages III and IV." (PMID 41322905, 2025). "IF staining revealed co-localization of Vimentin, p16, and CD81 in LIP gingiva, indicating the presence of senescent CD81+ fibroblasts in the experimental periodontitis model." (PMID 40801798, 2025). "To explore the communication between CD81+ fibroblasts and immune cells in periodontitis, we analyzed their interactions under diseased conditions." (PMID 40801798, 2025). "(A) The relative number of interactions between CD81+ fibroblasts and other cell types in periodontitis gingiva." (PMID 40801798, 2025). "This suggests that CD81+ fibroblasts play a key role in mediating the immune response during periodontitis." (PMID 40801798, 2025). "In conclusion, our study sheds light on the relationship between CD81 and cellular senescence, suggesting its potential as a therapeutic target for periodontitis." (PMID 40801798, 2025). "Our study focused on identifying a specific group of gingival fibroblasts that express high levels of CD81 during the development of periodontitis." (PMID 40801798, 2025). "Collectively, these findings suggest that metformin alleviates inflammation and bone resorption in periodontitis by inhibiting the interaction between CD81+ fibroblasts and neutrophils, which provides a novel therapeutic strategy for periodontitis." (PMID 40801798, 2025). "IF staining further showed that the proportion of CD81+ fibroblasts in periodontitis increased to approximately 50%, compared to very few in healthy samples." (PMID 40801798, 2025). "Conversely, decreased or stable expressions of CD81 and TSG101 were associated with clinical improvements in periodontitis, such as reduced probing depth." (PMID 38610017, 2024). "A recent study utilizing salivary sEV, isolated using an EQ kit, as potential biomarkers for periodontal disease status, suggested that CD9 and CD81 were decreased in periodontitis patient-derived sEV when compared with healthy controls." (PMID 32722322, 2020). "It is suggested that the decreased levels of CD9 and CD81 may disrupt molecular organization within the periodontal microenvironment, potentially contributing to tissue destruction and bone resorption in periodontitis." (PMID 41322905, 2025). "In human periodontitis gingiva, we found that CD81+ fibroblasts might activate neutrophils via the C3/C3aR1 axis to exaggerate inflammation." (PMID 40801798, 2025). "Thus, CD81+ fibroblasts might represent a core senescent fibroblast population in human periodontitis." (PMID 40801798, 2025). "Notably, CD81+ fibroblasts exhibited the highest expression of the C3 ligand compared to other fibroblast subgroups, while the C3 receptor (C3aR1) was exclusively expressed by neutrophils in periodontitis." (PMID 40801798, 2025).
periodontitis (continued). "Beyond the presence of immune-related proteins, salivary exosomes in periodontitis exhibit significantly reduced levels of the tetraspanins CD9 and CD81." (PMID 41322905, 2025). "(H) Hematoxylin and eosin (H&E) image and representative spatial mapping of CD81 and SOD2 in healthy and periodontitis gingiva from public dataset GSE206621." (PMID 40801798, 2025). "In patients with periodontitis, salivary samples demonstrated decreased levels of exosomal CD9 and CD81, when compared to healthy controls." (PMID 38610017, 2024). "According to another study, patients with periodontitis had considerably fewer CD9+ and CD81+ saliva exosomes than healthy controls." (PMID 37114060, 2023). "Overall, our bioinformatics analysis demonstrated that CD81+ fibroblasts exhibited differentiation arrest and heightened expression of SASP factors, further implicating them in the inflammatory and senescent processes of periodontitis." (PMID 40801798, 2025). "Interestingly, spatial transcriptomic analysis of gingival tissue revealed that the regions expressing CD81 and SOD2, a neutrophil marker, in periodontitis overlapped in the gingival lamina propria, showing a high spatial correlation." (PMID 40801798, 2025). "Salivary exosomal cargo in periodontitis includes complement components C6, C8A, C8B, and chemokine CCL28, together with decreased CD9/CD81 and elevated PD-L1 mRNA, which may indicate altered immune regulation and correlate with disease severity." (PMID 41322905, 2025). "Co-localization in CD81 and SOD2, a neutrophil marker, was found in the periodontitis gingiva." (PMID 40801798, 2025). "Additionally, this review found that salivary exosomal tetraspanins CD81 and CD9 were reduced in advanced periodontitis (stages II-IV, grade C), although only CD81 remained independently associated." (PMID 41322905, 2025).
bladder cancer (6 papers, 2012 to 2025). "In the Immune-response pathway, we observed an interaction between SNPs in GATA3 and CD81, such that the combined heterozygous variant genotypes were associated with reduced bladder cancer risk." (PMID 23284679, 2012). "A more recent study reveals that CD81 suppression promotes bladder cancer cell invasion through increased matrix metalloproteinase (MMP) expression." (PMID 32350244, 2020).
Infertility (6 papers, 2014 to 2023). "CD9 and CD81, closely related tetraspanins, are expressed abundantly in the lung, and both CD9 knockout (KO) and CD81 KO mice exhibit quite similar phenotypes, such as infertility." (PMID 29572511, 2018). "Interestingly, deletion of both CD9 and CD81 resulted in complete infertility, suggesting indirectly that these two surface molecules are interacting together, suggesting that the specific infertility is just a part of a more complicated situation." (PMID 25054321, 2014).
liver fibrosis (6 papers, 2012 to 2025). "miR-19a and miR-155 levels are associated with advanced liver fibrosis in the serum exosomes of HCV patients, and the CD81 protein content in serum exosome was positively associated with inflammatory activity and severity of liver fibrosis." (PMID 35571570, 2022). "In concordance, soluble CD81 levels were associated with higher stage liver fibrosis." (PMID 22355327, 2012). "Overall, soluble CD81 levels were associated with ALT levels (r = 0.334, p = 0.016) and severe liver fibrosis (p = 0.027)." (PMID 22355327, 2012). "Moreover, the CD81 protein content of exosomes was positively correlated with the grade of inflammation and the severity of liver fibrosis." (PMID 39599900, 2024). "Hepatitis virus infections leverage EV-encapsulated HBV-DNA and miRNA signatures (e.g., miR-21, miR-212) to detect occult infections and stratify liver fibrosis stages, while HCV-specific EV markers (CD81, miR-122) predict treatment response." (PMID 40809518, 2025). "Serum exosomal CD81 is increased in patients with chronic HCV, and its level correlates with the level of transaminases and severe liver fibrosis." (PMID 39599900, 2024).
colon cancer (5 papers, 2019 to 2025). "The expression ratio of transcripts SMAD4-209 and SMAD4-213 was suggested as a biomarker candidate for colon cancer detection, while another study proposed the CD81-215 transcript as a long non-coding RNA of stromal origin with a potential tumor-promoting role in colon cancer." (PMID 41050078, 2025). "In the current study, the CDEs isolated from human colon cancer cell line SW480 and HCT116 showed a size range of 60–150 nm, typical bilayer-encapsulated vesicles, and expressed the exosomal markers CD81 and CD63." (PMID 31402975, 2019).
colorectal cancer (5 papers, 2012 to 2026). A primary or metastatic malignant neoplasm that affects the colon or rectum. "EVs isolated from HT29 and SW480 colorectal cancer cell lines express CD81 and display differential levels of EpCAM by Western Blotting as well as by ELEXO." (PMID 34155195, 2021). "In the present study, we investigated the tetraspanin family proteins CD63, CD9 and CD81 as useful collection markers of exosomes derived from the three colorectal cancer (CRC) cell lines HCT-15, SW480 and WiDr." (PMID 22895844, 2012). "This could be explained by our selection of the CD81-expressing EV population, which was increased and thus detectable in cancer patients’ CD81sEV, or by the higher levels of these two FAs in the CD81sEV, as shown in the sera of colorectal cancer patients." (PMID 34439311, 2021).
HIV-1 infection (5 papers, 2009 to 2024). The type species of lentivirus and the etiologic agent of acquired immunodeficiency syndrome (AIDS). "In light of previous findings, we assessed CD81 localization during HIV-1 infection." (PMID 32075937, 2020). "CD81 associates with CD4 and is critical for HIV-1 infection." (PMID 29429034, 2018). "We showed that CD81 downregulation decreased virus production by 3-fold and the resulting virus was more infectious, suggesting that CD81 tetraspanin incorporation is able to modulate HIV-1 infection, as this was recently proposed for HIV-1 infected CD4+ activated lymphocytes." (PMID 19284574, 2009). "However, the downregulation of CD81 allowed the virus to be more infectious, suggesting that CD81 could also act as a cellular defense response against HIV-1 infection." (PMID 19284574, 2009).
antibody deficiency (4 papers, 2014 to 2023). "The function of CD81 was confirmed in a patient carrying a homozygous mutation of the CD81 gene which caused the syndrome of antibody deficiency by disrupting the CD19 complex in B cells and impairing BCR activation although the CD19 alleles in the patient are normal." (PMID 30072987, 2018). "Other studies have previously shown that deficiency in genes involved in B-cell receptor sequencing (CD19, CD21, CD81, PLCG2, PI3KCD) can lead to CVID-like antibody deficiencies." (PMID 26122175, 2015).
benign prostatic hyperplasia (4 papers, 2021 to 2024). A non-cancerous nodular enlargement of the prostate gland. "Patients with prostate cancer have been found to have a four-fold higher level of nanovesicles expressing PSA and CD81 as compared to healthy men or those with benign prostate hypertrophy (BPH)." (PMID 37834162, 2023). "The size and the tetraspanin content, in particular CD9, CD81, CD63 and CD41a are different in exosomes collected from benign prostatic hyperplasia, localized PC (LPC) and advanced prostate cancer (AdvPC; 58)." (PMID 34772427, 2021).
breast tumor (4 papers, 2018 to 2024). "Like CD44KO cells, CD81 KO populations decreased protein levels of breast tumor-initiating markers including OCT4, NOTCH1, and phosphoSTAT3." (PMID 36193887, 2022). "Consistent with the observations in 4T1/67NR mouse models, breast tumors with signatures of low CD81+CD63+EVs had a significantly higher frequency of M2 macrophages (known to differentiate from M-MDSCs) compared with tumors with signatures of high CD81+CD63+EVs." (PMID 34503207, 2021). "Additionally, immunofluorescence analysis of breast tumours showed that BHS synergized with paclitaxel to significantly decrease the expression levels of CD81, CXCL1, and CD204, suggesting that BHS suppressed paclitaxel‐induced EV‐Apo biogenesis, CXCL1 secretion, and TAM infiltration." (PMID 39051750, 2024). "We also conducted a primary breast tumor tissue microarray (TMA) study and observed a correlation of CD44 and CD81 expression across tumor subtypes (TNBC, HER2, luminal A/B) as well as an upregulated expression of CD44/CD81 in TNBC in comparison to luminal A/B." (PMID 36193887, 2022). "In human non-metastatic breast tumors, tumors enriched in signatures of CD81+CD63+EV have a better prognosis, higher immune cytolytic activity, and enrichment of pro-inflammatory macrophages compared with tumors with low CD81+CD63+EVs signatures." (PMID 34503207, 2021). "Notably, expression of the CD81 interactor and HCV entry facilitator CBLB is altered in gastric and breast tumor tissue and CBLB regulates cell migration and epidermal to mesenchymal transition (EMT) through EGFR degradation." (PMID 30024968, 2018).
diabetes (4 papers, 2018 to 2025). "CD9, CD63, CD81, and CD41a expression progressively decreased in the Healthy, Diabetes, and DFU groups, respectively." (PMID 39835574, 2025). "Recent studies have suggested that CD81 is a marker of dedifferentiated β-cells under conditions of metabolic stress, such as progressive diabetes." (PMID 38066741, 2023). "Some known markers were not state-specific, such as certain immature marker genes that were also highly expressed in the db/db + mSTZ state (for example, Cd81), in accordance with β-cell dedifferentiation in mouse diabetes models." (PMID 37697055, 2023). "The significant increase in exosome marker proteins CD81 and HSP70 in exosomes from diabetic rats suggests an overall increase in exosome quantity in the setting of diabetes." (PMID 28840975, 2018).
HCMV infection (4 papers, 2017 to 2022). "Peptides comprising the C-terminal CD9 and CD81 peptide had only minor effects on HCMV infection." (PMID 30279342, 2018). "However CD81 peptide significantly increased HCMV infection in EAhy926 cells, which might be a cell line specific effect." (PMID 30279342, 2018). "It has been shown that CD9, CD81 and CD151 were downregulated during HCMV entry and that cellular depletion of CD9, CD63 and CD151 reduced HCMV infection." (PMID 30279342, 2018). "Nevertheless, HCMV infection with AD169 did reduce the steady state levels of caveolin-1 as well as CD98, CD44, and CD81 as shown by Western blotting of whole cell lysates." (PMID 29121670, 2017). "Furthermore, we analyzed the involvement of specific tetraspanin domains, the LEL and the C-terminus, in HPV and HCMV infection by using recombinant peptides or proteins comprising these domains of CD9, CD63, CD81 and CD151 tetraspanins." (PMID 30279342, 2018). "CD81 is a tetraspanin, like CD151 and CD9 that were also downregulated upon HCMV infection." (PMID 29121670, 2017). "In this study we compared the importance of tetraspanins CD9, CD63, CD81 and CD151 in infections by human papilloma- and cytomegalovirus and investigated whether peptides of functional tetraspanin domains could be used as inhibitors of HPV and HCMV infection." (PMID 30279342, 2018).
influenza (4 papers, 2008 to 2018). An acute viral infection of the respiratory tract, occurring in isolated cases, in epidemics, or in pandemics; it is caused by serologically different strains of viruses (influenzaviruses) designated A, B, and C, has a 3-day incubation period, and usually lasts for 3 to 10 days. "Two members of the tetraspanin family, CD9 and CD81, were found to be associated with influenza virions and are most likely inserted into the viral envelope." (PMID 18535660, 2008). "In this work, we examined the effect of CD81 depletion on the major steps of the influenza infection." (PMID 24130495, 2013). "Taken together, these results demonstrate important roles of CD81 in both entry and budding stages of the influenza infection cycle." (PMID 24130495, 2013). "The specific role of CD81 during influenza viral entry was determined using a series of independent assays." (PMID 24130495, 2013). "We found that CD81 was important for influenza infection at two distinct stages: virus uncoating and virus budding." (PMID 24130495, 2013). "Next, we proceeded to determine which stage(s) of the multi-step influenza-infection process is CD81-dependent." (PMID 24130495, 2013). "We conducted a comprehensive study from viral entry to egress to examine the effect of CD81 depletion on influenza infection." (PMID 24130495, 2013). "Moreover, influenza infection induced redistribution of CD81 on the plasma membrane into concentrated patches of viral budding sites which also contain different viral proteins." (PMID 29887866, 2018). "To test whether CD81 affects early infection, we infected siRNA-treated A549 cells and measured the expression of NP, the first viral protein expressed in influenza-infected cells." (PMID 24130495, 2013). "Alternatively, CD81 may play a role in trafficking influenza to fusion competent endosomal compartments." (PMID 24130495, 2013). "In addition to its role in virus uncoating, CD81 also plays a functional role in a later stage of influenza infection post viral fusion." (PMID 24130495, 2013). "Given that CD81 and CD81-associating proteins can organize membrane domains, CD81 may help organize the endosomal membrane for assisting influenza viral fusion." (PMID 24130495, 2013). "Altogether, these results indicate that CD81 plays a role in influenza viral fusion." (PMID 24130495, 2013). "In this work, we studied the role of the host protein CD81 in influenza infection." (PMID 24130495, 2013). "Here, CD81 may help organize the endosomal membrane and cofactors assisting influenza viral fusion." (PMID 29887866, 2018). "To probe whether CD81 plays additional roles beyond viral uncoating, we induced influenza viral fusion at the plasma membrane using the acid-bypass treatment to overcome the entry defect, and determined the virus titer of the supernatant 17 hours post-infection." (PMID 24130495, 2013). "Taken together, these data indicate that CD81 does not play a direct role in the expression of influenza viral proteins or the trafficking of influenza membrane proteins to the plasma membrane." (PMID 24130495, 2013). "The defect was not due to direct regulation of viral protein expression by CD81, since viral protein expression remained unchanged upon CD81 knockdown when influenza infection was induced by the acid-bypass treatment." (PMID 24130495, 2013). "The exact role played by CD81 in influenza infection, however, has not been elucidated thus far." (PMID 24130495, 2013).
lung adenocarcinoma (4 papers, 2020 to 2024). A carcinoma that arises from the lung and is characterized by the presence of malignant glandular epithelial cells. "This study is the first to elucidate the role of tetraspanins in TILs within the TME of patients with non-small cell carcinoma, following the observation of CD81 expression in the innate immune landscape of lung adenocarcinoma." (PMID 38515751, 2024). "Lung adenocarcinoma-derived exosomal miR-19b-3p (size range of 100 nm, marker proteins CD9, CD81) and miR-10b (bilayer membrane structure, typical “cupped” structure, marker proteins TSG101,CD63,CD81) facilitate macrophage polarization to the M2 type to promote lung adenocarcinoma development." (PMID 39165926, 2024).